TNF (tumor necrosis factor)
Diseases named in the same sentence as TNF in open-access papers (continued):
Sharing a sentence is not in itself a finding about the gene and the disease.
Obesity (continued). "In obesity condition, it is observed a disbalance on this secretion, where a greater release of pro-inflammatory cytokines (Leptin, IL-6, TNF-α among others) is seen in detriment to anti-inflammatory cytokines (Adiponectin and IL-10)." (PMID 31749764, 2019). "In a recent study, fucoxanthin, at a dose of 0.6% during four weeks, significantly inhibited obesity by the decrease of inflammatory markers production such as TNF-α and cyclo-oxygenase-2 (COX-2) in HF-fed mice." (PMID 31091691, 2019). "We conclude that TTIp presented anti-TNF-α activity and an improved lipid profile of Wistar rats with dyslipidemia and obesity induced by a high glycemic index and load diet regardless of PPAR-γ induction." (PMID 30818882, 2019). "In this study, we demonstrated that FGF-1 treatment significantly ameliorated obesity and TNF-α-induced stimulated cytokine secretion such as TNF-α and IL-6 as well as enhancing anti-inflammatory." (PMID 31866871, 2019). "Decreased expression of TWIST1 results in elevated secretion of TNFα, which is responsible for the progression of obesity and insulin resistance." (PMID 30678306, 2019). "First, adipose tissue is an important source of proinflammatory cytokines including tumor necrosis factor-alpha (TNFα), interleukin-(IL)-6 (IL-6) and IL-8 (CXCL8), which contribute to obesity-associated ‘smoldering’ inflammation." (PMID 31234447, 2019). "Obesity adds to the genetic susceptibility, insulin resistance due to FFA and tumor necrosis factor -α (TNF-α), an inhibitor of insulin receptor kinase activity, leptin-regulating hormone appetite and adiponectin." (PMID 30931309, 2019). "It has been demonstrated previously that increased renal and adipose tissue TNFα production is attributed to infiltrating pro-inflammatory macrophages contributing to obesity-related renal impairment." (PMID 31480394, 2019). "It is well-established that both HFDs and obesity incite a chronic, low-grade inflammatory state due to upregulated NFkB and subsequent secretion of inflammatory cytokines such as IL-1, IL-6, and TNF." (PMID 31196172, 2019). "Recent studies have shown associations between markers of metabolic endotoxemia (LBP and sCD14) and systemic inflammation (TNF-α and IL-6) in subjects with obesity and metabolic syndrome." (PMID 31372515, 2019). "Obesity is a chronic state of low-grade inflammation with sustained and significantly higher level of inflammatory cytokines like TNFα that is known to directly inhibit adiponectin transcription." (PMID 31121868, 2019). "On the other hand, obesity induced cytokines production, such as TNF-α that can blunt transportation of L-arginine into the endothelial cell which further contributes to diminished NO production." (PMID 30856212, 2019). "Macrophages represent a large proportion of the immune cell population in PVAT, and in obesity macrophages are the main source of TNF-α and IL-6." (PMID 30747398, 2019). "TLR2/4 activation causes a proinflammatory response in autoimmune diseases and contributes to an obesity-induced inflammatory response by increasing TNF-a and IL-6 levels in RA and TNF-a, IL-6, IL-23, and IL-10 levels in SLE." (PMID 31788032, 2019). "A persistent increase of circulating levels of tumor necrosis factor-alpha (TNF-α) occurring during obesity or aging has an important role in pathogenesis of systemic insulin resistance." (PMID 31453381, 2019). "Obesity-induced chronic inflammation leads to overexpression of TNFα (tumor necrosis factor alpha), IL6 (interleukin 6), IL18 (interleukin 18), and other pro-inflammatory cytokines that are also known to inhibit adiponectin." (PMID 31121868, 2019). "For example, tumor necrosis factor-α (TNF-α) is an adipo-cytokine involved in inflammation and is found to be increased in the metabolic syndrome, T2D and obesity, and therefore contributes to insulin resistance by interfering with insulin receptor signaling." (PMID 30678182, 2019).
Obesity (continued). "Obesity increases leptin secretion from adipocytes and proinflammatory cytokines, such as tumor necrosis factor and interleukins 1 and 6, from macrophages and leukocytes." (PMID 31906216, 2019). "Obesity results in elevation of inflammatory cytokines such as interleukin-6 (IL-6), tumor necrosis factor-alpha, (TNFα), and interleukin-1 beta (IL-1β), which have all been linked to the development of breast cancer." (PMID 31007849, 2019). "Administration of nicotine (an α7nAChR agonist) to genetically obese db/db mice lacking the leptin receptor and mice with high-fat diet-induced obesity suppresses adipose tissue and systemic TNF levels." (PMID 31024226, 2019). "Like senescent cells, these immune cells release inflammatory mediators, including TNF‐α and osteopontin, which can contribute to obesity‐related insulin resistance." (PMID 30907060, 2019). "TNF-α is the most highly secreted cytokine during obesity and was the first inflammatory cytokine linking obesity-induced inflammation to IR." (PMID 31159253, 2019). "Overall, TLR8ko pDCs and cDCs have higher TLR7 expression than WT cells, whereas HFD-mediated obesity leads to an increase of TLR7+TNF+ pDCs and cDCs, and this is more profound in TLR8ko than in WT mice." (PMID 31552019, 2019). "In diet-induced obesity models, forced exercise reduced TNF-α and T cell expression, macrophage infiltration and induced a phenotypic switch of M1 macrophages to M2." (PMID 30747398, 2019). "Adipose tissue of individuals with obesity exhibit elevated expression of TNF-α, IL-6, CCL2, FFAs, and IL-8 when compared with normo-weight controls." (PMID 31443599, 2019). "One characteristic of hypoxia in obesity is an increase in expression of pro-inflammatory cytokines such as tumour necrosis factor alpha (TNF-α) and interleukin-6 (IL-6)." (PMID 30747398, 2019). "TNF-α plays a key role in obesity-related insulin resistance and increased TNF-α levels contribute to impaired glucose homeostasis." (PMID 31557884, 2019). "Both IL-6 and TNF-α levels can be increased in obesity, and both cytokines can cross the blood–brain barrier by a saturable transport mechanism." (PMID 31739649, 2019). "We here assessed the effect of OC and OA on the expression of inflammation-related genes (transcripts) and miRNAs in human adipocytes, under an obesity-mimicking inflammation induced by the cytokine TNF-α." (PMID 31766503, 2019). "Fatty acids and TNF-α have been shown to induce M1 polarization in obesity but also glucose, insulin, and obesity-induced hypoxia trigger macrophages toward a pro-inflammatory phenotype." (PMID 31333642, 2019). "Several studies have demonstrated consistently higher levels of IL-8, FFAs and TNF-α in the circulation of individuals with obesity/T2D and we recently showed that coexistent of TNF-α and saturated fatty acids enhanced CCL2 production." (PMID 31443599, 2019). "Metabolic disorder and inflammation cause IR and promote leukocytes to secrete proinflammatory cytokines, including IL-6 and tumor necrosis factor-α (TNF-α), which provides a framework to understand how physiological stress, obesity, and diet promote IR." (PMID 31258478, 2019). "In the present study, we investigated the effects of administering recombinant FGF-1 to obesity- or TNF-α-induced insulin resistance mouse models, and our findings indicated that FGF-1 significantly improves insulin resistance and reduces inflammation." (PMID 31866871, 2019). "Regarding the mechanism of TNF-α in promoting tumorigenesis and development, it has been reported that chronic inflammation induced by obesity promotes the accumulation of macrophages in adipose tissue." (PMID 31440472, 2019). "Studies in humans have suggested that adipose-derived TNFα represents a link among obesity, inflammation, and diabetes, and increased expression levels of TNFα in AT of obese subjects have been strongly implicated in the pathogenesis of IR." (PMID 31114678, 2019).
Obesity (continued). "As in adipose tissue, macrophages infiltrate and accumulate in pancreatic islets of obese T2DM individuals and diet-induced obesity mice, which produce proinflammatory cytokines and chemokines, such as TNF-α, IL-1β, and MCP1." (PMID 31582899, 2019). "It is reported that the TNFα cytokine is secreted by adipose tissue and plays an essential role in mediating insulin resistance and as a result of obesity." (PMID 32133054, 2019). "Recently, our group demonstrated that GT prevents obesity and improves adipose tissue metabolism through the miR-335 regulation mediated by TNF-α repression." (PMID 31885789, 2019). "In the context of SLs and obesity, TNF alpha/IL 10 balance counteracts the up-regulation of acid SMase, neutral SMase and SPT and the increment of Cer." (PMID 31771303, 2019). "The relationship between obesity, periodontal status and serum IL-6 remains controversial due to the role of TNF-α." (PMID 31365708, 2019). "Obesity in cats has been associated with alterations in adipokines including: adiponectin, interleukin-6 (IL6), and tumor necrosis factor-α (TNFα)." (PMID 31492181, 2019). "When compared by BMI groups, gamma-linoleic acid (18:3n6) was negatively correlated with insulin (β = -3.59, R2 = 0.50, p<0.05) and positively correlated with TNF-α (β = 0.60, R2 = 0.39, p<0.05) among women with overweight and obesity only." (PMID 31141526, 2019). "In a high-fat-diet-induced obese mouse model empagliflozin reduced plasma TNF alpha levels and attenuated obesity-related chronic inflammation." (PMID 30922297, 2019). "Studies have shown that TNF-α plays an important role in obesity-induced insulin resistance by promoting the serine phosphorylation of IRS-1." (PMID 30871060, 2019). "Obesity can lead to tissue hypoxia, followed by induction of a series of inflammatory cytokines, such as tumor necrosis factor-α (TNF-α) and interleukins." (PMID 31466366, 2019). "TNF-α increases miR-155 expression in adipocytes, which results in obesity progression in female mice by limiting BAT differentiation." (PMID 31806859, 2019). "In contrast, other studies in cats reported decreased circulating concentrations and adipose tissue mRNA expression of adiponectin and increased expression of TNFα in obesity." (PMID 31492181, 2019). "In the study by Carvalho, besides the reduction of food consumption in animals with obesity and SM, the effect on TNF-α reduction and the lipid profile was observed for TTI." (PMID 30818882, 2019). "Previous literature has postulated that obesity is related to low-grade inflammation, which probably results in an increased serum TNF-α level." (PMID 31652851, 2019). "It has been supported by the fact that in obesity and high-fat diet, removal of TNF-α function improves insulin sensitivity and glucose homeostasis in obese mice." (PMID 30863203, 2019). "Inflammatory cytokines including C-C chemokine ligand 2 (CCL2), TNF-α, and interleukin-6 are increased in obesity." (PMID 31498850, 2019). "In order to model the low-grade inflammation observed in obesity, the secretome of adipocytes exposed to TNFα in 2D and 3D culture was assessed." (PMID 32133436, 2019). "Due to obesity, the levels of adipocytes, cytokines (interleukin-1 (IL-1) and interleukin-6 (IL-6)), and tumor necrosis factor alpha (TNFα)) increases in the body." (PMID 31470636, 2019). "There is also an increase in secretion of pro-inflammatory hormones such as the thyroid hormone and cytokines (leptin, tumor necrosis factor (TNF)-α, and interleukin (IL)-6) in obesity." (PMID 31817534, 2019). "TNF-α and IL-6 are cytokines that are synthesized in ATM and increased with lipid accumulation; thus, these cytokines are indicators of obesity-associated inflammation." (PMID 30889894, 2019). "Significant biomarkers of inflammation (hsCRP, IL-6, and TNF-alpha) and endothelial dysfunction (sICAM-1 and sVCAM-1) are present in young children with obesity." (PMID 30625218, 2019).
Obesity (continued). "Specifically, BAIBA treatment led to declines in plasma levels of TNFα in mice with high-fat diet-induced obesity." (PMID 30823446, 2019). "TNFα as a contributor to oxidative stress, either directly or indirectly plays an important role in the progression of obesity." (PMID 31391086, 2019). "Obesity is known to feature a chronic inflammatory process, with increased levels of proinflammatory cytokines (TNF-α, IL-6, IL-12), generation of reactive oxygen species, and greater differentiation of activated macrophages into the M1 phenotype." (PMID 31138279, 2019). "Given the known carcinogenic nature of the inflammatory cytokine TNF, derived from macrophages that infiltrate adipose tissue, these data are consistent with an immunologic mechanism linking obesity and breast cancer." (PMID 31555578, 2019). "In the same study, 14-day treatment with etanercept, a TNF-α blocker, similarly improved islet insulin secretion in the obesity-single-low dose streptozotocin model." (PMID 30989320, 2019). "An interesting study showed that obesity modulates the expression of HP in white adipose tissue via TNFα." (PMID 31504048, 2019). "Early efforts to disentangle the close relationship between obesity and type II diabetes focused on the pro-inflammatory cytokine tumor necrosis factor alpha (TNF-α) in visceral white adipose tissue (vWAT)." (PMID 31225498, 2019). "TNF is a factor involved in diet-induced obesity and insulin resistance as well as in low-grade inflammation related to adipose tissue expansion." (PMID 31093012, 2019). "Fibrates and thiazolidinediones (TZDs) activate intracellular nuclear receptors such as PPARγ and TZDs, and reduce the expression of leptin and TNF-α, thereby reducing the inflammatory process by obesity." (PMID 30818882, 2019). "In patients with obesity, hypertrophic adipocytes produce several cytokines and chemokines, such as interleukin (IL)-6, tumor necrosis factor-α (TNF-α), IL-1β, and monocyte chemoattractant protein-1 (MCP-1)." (PMID 31775341, 2019). "Obesity can also enhance bone resorption by the increase of pro-inflammatory cytokine levels [Tumor Necrosis factor alpha (TNFα) and interleukin-6 (IL-6)], which promote osteoclast formation and activity by affecting RANKL/RANK/OPG pathway." (PMID 31130918, 2019). "Pro-inflammatory hormones and cytokines (leptin, tumor necrosis factor (TNF)-α, and interleukin (IL)-6) rise in obesity." (PMID 31817534, 2019). "In the present study, significant correlation was observed between serum IL-6 and TNF-α and this correlation remained significant even after controlling for the possible confounders, such as age, sex, BP and obesity markers." (PMID 30635365, 2019). "Functional studies revealed that synthetic single-stranded miR mimics for conserved plant miR156c and 159a are able to inhibit the TNF-α signaling pathway through the targeting of Tnfrsf1a gene transcript in experimental models of obesity." (PMID 31453381, 2019). "TNFα plays a key role in the inflammatory processes that are present in obesity, dyslipidaemia, insulin resistance and cardiometabolic disease." (PMID 31344895, 2019). "On the other hand, activation of TLR-4 in adipose tissues occurs through interactions with gut microbiota LPS or adipocyte lipolysis-released free fatty acids, which can induce the secretion of inflammatory adipocytokines (i.e., IL-6 and TNF) in obesity." (PMID 31632356, 2019). "Pro-inflammatory cytokines, such as tumor necrosis factor alpha (TNF-α) and interleukin six (IL-6), have often been associated with obesity." (PMID 31141526, 2019). "We found that the levels of MCP‐1, IL‐6 and TNF‐α in obese mice (Obesity) were 1.51, 1.75 and 1.43‐fold higher than those in normal control mice (Control), respectively." (PMID 31270932, 2019). "It was proven that Dec1KO mice suppressed inflammation in periodontitis and obesity by decreasing inflammatory factors such as TNFα, IL-1β, and peroxisome proliferative active receptor gamma (PPARγ)." (PMID 31597354, 2019).
Obesity (continued). "TNFα is another inflammatory cytokine secreted by immune cells and has been shown to be positively correlated with obesity and T2D." (PMID 30728429, 2019). "LPS can bind and activate TLR-4 to increase the expression of pro-inflammatory mediators such as TNF-α, and these pro-inflammatory mediators can interfere with the binding of insulin to its receptor, leading to IR and obesity." (PMID 30744700, 2019). "In vitro treatment of KCs with FFAs (e.g., palmitate) promotes activation and secretion of inflammatory cytokines (e.g., IL-6, TNF, IL-1β) while KC depletion in vivo protects from obesity-driven hepatic steatosis." (PMID 31921154, 2019). "Studies show that obesity increases the inflammatory marker tumor necrosis factor (TNF)-alpha as well as inflammatory cells in the testicles that contribute to Leydig cell damage, inhibition of LH signaling, and thus reduced testosterone production." (PMID 31052376, 2019). "Many health benefits have been associated with purple corn, including reduction of drug-induced cardiotoxicity and trigeminal inflammation, prevention of obesity and diabetes and reduction of TNF-α-induced inflammation in adipocytes in vitro." (PMID 31337415, 2019). "Tumor necrosis factor-α (TNF-α), interleukin (IL) −6 and −8 are pro-inflammatory proteins that are increasingly synthesized by adipocytes in obesity and play a role in insulin resistance and lipolysis." (PMID 30622707, 2019). "The recruited ATMs secrete both anti-inflammatory (interleukin-10 (IL-10) and IL-1) and pro-inflammatory (tumor necrosis factor-α (TNF-α), IL-6, and IL-1β) cytokines, suggesting they can serve both a protective and harmful role in obesity." (PMID 32133436, 2019). "It has been implicated that obesity can upregulate circulating CCL2 and TNF-α, the cause of obesity-associated insulin resistance and the development of type 2 diabetes." (PMID 31498850, 2019). "Obesity is related to low-grade chronic inflammation, which contributes to insulin resistance by adipocytokines functions such as tumor necrosis factor alpha (TNFα) and adiponectin." (PMID 32133054, 2019). "In contrast to adiponectin, levels of several other adipokines including tumour necrosis factor-α (TNF-α) increase in obesity." (PMID 30871282, 2019). "Obesity itself is characterized by an inflammatory response in which crucial mediators of inflammation like tumor necrosis factor-alpha (TNF-α) show significant patterns of expression in both animal models and humans." (PMID 31551782, 2019). "The activation of the inflammatory process is responsible for the formation of atherosclerotic changes in obesity, which can be confirmed by an increase in the level of pro-inflammatory cytokines, including tumor necrosis factor α." (PMID 31737129, 2019). "It is known that tumour necrosis factor alpha (TNF-α)—a cytokine that is elevated in patients with psoriasis, rheumatic diseases, and obesity—induces insulin resistance through various mechanisms." (PMID 31275060, 2019). "Based on the in vitro findings, which demonstrated the capacity of nut NVs to down-regulate TNF-α signaling, we next moved at analyzing the effects of such NVs in an in vivo model of diet-induced obesity." (PMID 31453381, 2019). "Several lines of evidence suggest that interferon-γ (IFNγ) and tumor necrosis factor-α (TNFα) levels are markedly increased in obesity." (PMID 31504048, 2019). "The discovery of high TNFα levels in the adipose tissue of obese mice offered the initial demonstration of a cross-talk between obesity and inflammation." (PMID 31130918, 2019). "Increased levels of GM3 in 3T3-L1 adipocytes upon tumor necrosis factor-alpha (TNFα) stimulations were found to induce insulin resistance in proinflammatory conditions such as obesity." (PMID 31013778, 2019). "Although several pathways between TNF-α and tumors have been identified, the precise mechanism of obesity-related TNF-α involved in the development of endometrial cancer remains to be further investigated." (PMID 31440472, 2019).